CDC7 (cell division cycle 7)
Diseases named in the same sentence as CDC7 in open-access papers (continued):
Sharing a sentence is not in itself a finding about the gene and the disease.
cancer (continued). "In this paper, we unveiled a novel role of Cdc7-Dbf4 in the regulation of ATR/ATM checkpoint signaling and HR DNA repair in cancer by phosphorylating HSP90 at S164." (PMID 29209046, 2017). "We provide a new solution to a subtyping of cancer patients with dominant ATR/HSP90 expression by combining inhibitors of ATR-Chk1, HSP90, or Cdc7 in cancer combination therapy." (PMID 29209046, 2017). "Depletion of Cdc7 in HeLa, U2OS or other cancer cells with siRNA resulted in inhibition of DNA synthesis, accumulation of chromosome damages [represented by γ-H2AX foci) and eventual loss of viability viability." (PMID 22574151, 2012). "CDC7 inhibitors have been successfully administered to patients with solid tumors, whereas UHRF1 inhibitors require further studies to determine their application in cancer treatment." (PMID 36725843, 2023). "CDC7 inhibitors have shown antitumor effects in various cancers; however, no study has explored the role of CDC7 and its inhibition in SCLC." (PMID 36725843, 2023). "Indeed, one strategy that has been successfully employed in animals it to first render cancer cells senescent using chemotherapeutics, PARP inhibitors or CDC7 inhibitors, followed by the elimination of these induced senescent cells using senolytic compounds." (PMID 36980201, 2023). "Indeed, several previous studies in human immortalized or cancer cells have suggested a function of ATR and CHK1 in controlling replication initiation and origin firing by counteracting CDC7 or CDK1 activties." (PMID 37336885, 2023). "Therefore, understanding the detailed structural and molecular mechanisms of Cdc7 activation by Dbf4, the docking of the DDK onto the DH, and the activation of DH by DDK would be invaluable for developing anti-cancer drugs." (PMID 35296675, 2022). "Small molecule Cdc7 inhibitors selectively promote apoptosis in cancer cells without activating apoptosis in healthy cells." (PMID 36009559, 2022). "We found four paired lncRNA-mRNA exhibiting a substantially high SCNA frequency in cancers, including lncRNA FGD5-AS1 and PRKAR2A (KIRC, 44.2% and 44.4%), lncRNA TUG1 and CDC7 (LUAD, 25.9% and 23.6%), lncRNA TUG1 and DSC2 (LUAD, 25.9% and 26.1%) and lncRNA SNHG7 and PNMA2 (LUAD, 25.4% and 31.1%)." (PMID 32846981, 2020). "We also show that, whereas Cdc7 is predominantly responsible for CKBD phosphorylation in cancer cells, CK1γ1 plays a major role in non-cancer cells, providing rationale for targeting Cdc7 for cancer cell-specific cell killing." (PMID 31889509, 2019). "Evidence has shown that Cdc7-selective inhibitors may decrease MCM2 phosphorylation, inhibit DNA synthesis, and cancer cell viability." (PMID 30062004, 2018). "We further found that highly-upregulated Cdc7 promotes not only HR DNA repair but fork recovery, replication restart, and TLS during replication stress, which enhances DNA damage tolerance and cell survival in cancer." (PMID 29209046, 2017). "The inverse correlation of miR-630 and CDC7 expression occurred in several cancer and immortalized cells even in the absence of DNA damage agents." (PMID 25255219, 2014).
cancer (continued). "As DDK is an obvious target for cancer therapy, information about the unique features of Dbf4 in regulating Cdc7 activities provides the necessary details for developing novel anti-cancer drugs that selectively kill cancer cells with low toxic off-target side effects." (PMID 35296675, 2022). "Cdc7 inhibition or depletion reduces DNA synthesis both in cancer and non-cancer cells." (PMID 31889509, 2019). "The crucial role of Cdc7 in checkpoint activation in cancer cells but not in non-cancer cells may provide molecular explanation for cancer cell-specific cell death induced by Cdc7 inhibition." (PMID 31889509, 2019). "In this study, we provided the compelling evidence that Cdc7-Dbf4 interacts with HCLK2-HSP90-Mre11 complex and phosphorylates HSP90-S164 to enhance ATR/ATM checkpoint signaling, HR DNA repair, and checkpoint recovery, which enhances replication stress tolerance for the survival of cancer cells." (PMID 29209046, 2017). "However, the downstream targets of Cdc7-Dbf4 contributed to checkpoint regulation and replication stress-support function in cancer are not fully identified." (PMID 29209046, 2017). "By demonstrating a major role for PP1 in the regulation of Cdc7 activity, our work also has implications for the best use of DDK inhibitors as anti-cancer agents, in particular suggesting that modulation of PP1 activity could enhance their therapeutic efficacy." (PMID 24403013, 2014).
tumor (53 papers, 2012 to 2026). "demonstrate that loss of FBXW7 in tumour cells imparts a synthetic lethal effect with CDC7 inhibition." (PMID 37866880, 2024). "CDC7 expression is high in GBMs, it is required for tumor proliferation, implicated in radio-resistance, invasion and tumor growth." (PMID 33804958, 2021). "A mounting evidence indicts the overexpression of CDC7 in tumor cells and its relation with the increase in mutational frequency and therefore promotes tumorigenesis and chemoresistance." (PMID 31578454, 2019). "Taken together these findings indicate that targeting Cdc7 constitutes a synthetic lethality driven approach in tumour backgrounds harbouring commonly mutated tumour suppressor genes." (PMID 26921250, 2016). "Loss of Cdc7 expression was significantly associated with high tumor stage (p < 0.0001) and high tumor grade (p = 0.0077), but was unrelated to the nodal status (p = 0.5957)." (PMID 26208856, 2015). "We hypothesized that indirect suppression of MCM2‐MCM7 hexamer function caused by CDC7 inhibition may decrease tumor cell progression." (PMID 37517032, 2023). "Indeed, overexpression of Cdc7-Dbf4 is associated with tumor advanced clinical stage, patient survival, cell cycle deregulation, and genomic instability." (PMID 29209046, 2017). "Cdc7 and Dbf4 overexpression are reported to cause cell-cycle arrest in S phase and it has been hypothesized that increased Cdc7 activity may aid recovery or repair of stalled replication forks to enhance survival of tumor cells." (PMID 26208856, 2015). "Therefore, it can be assumed that alterations in Cdc7/Dbf4 protein activity during tumorigenesis may have important consequences for tumor cell survival, underlining the potential of Cdc7 as an anticancer target." (PMID 26208856, 2015). "CDC7-bound PGK1 rescues the assembly and activity of CDC7 complex and recruits DNA helicase to initiate DNA replication and accelerate tumor development." (PMID 40612109, 2025). "In HCC models, sertraline enhanced therapeutic efficacy when combined with CDC7 inhibition by promoting apoptosis in senescent tumor cells through mTOR suppression." (PMID 40874450, 2025). "CDC7 knockdown in TD-NEPC and DU145-RFP cell lines was associated with slower xenograft tumor growth and size compared to parental and shControls." (PMID 41413594, 2025). "The enhanced anti‐tumor effects of Olaparib in combination with CDC7 inhibition hold promise for the development of more effective therapeutic strategies against OV." (PMID 39412086, 2024). "Given the correlation between activation of cGAS/STING signaling and type I interferon innate immune responses, we next sought to assess the effects of Olaparib in combination with CDC7 inhibition on anti‐tumor immunity in vitro." (PMID 39412086, 2024). "In fact, reduction of replication origins, through Cdc7 inhibition, in Shh-exposed GCPs blocks replication stress along with MB initiation in tumor-prone mice." (PMID 39594660, 2024). "The differences in DBF4 and CDC7 expression in tumor tissues and adjacent normal tissues were analyzed." (PMID 36609254, 2023). "The results of xenograft tumor models and HDRAs using PDXs indicated that combined treatment with a CDC7 inhibitor and chemotherapy is effective in mouse models and patient-derived tissues." (PMID 36725843, 2023). "As shown, the expression of DBF4 and CDC7 was positively correlated with tumor grade and stage, and was much higher in advanced HCC patients with higher clinical stage and grade." (PMID 36609254, 2023). "Our study found six genes (PCNA, CDC6, CDC7, CDT1, CDK2, and RBBP8) that were most significantly linked with expression levels of key genes and tumor progression." (PMID 37656243, 2023). "To investigate the expression of DDK complex members in HCC patients, we firstly sorted out the expression profile of DBF4 and CDC7 in TCGA dataset, and we found both DBF4 and CDC7 were significantly highly expressed in HCC tumor tissues." (PMID 36609254, 2023).
tumor (continued). "In this study, the inhibitor of CDC7 increased DNA replication stress and then sensitized tumor cells to ATR or CHK1 inhibitors, respectively." (PMID 37153782, 2023). "In tumors cells, the appropriate response of CDC7 to replication stress plays an important role in tumor transformation by triggering a series of replication activation and ATR–CHK1 checkpoint responses." (PMID 36426371, 2022). "Recently, the CDC7 inhibitor TAK-931 has also been shown to improve responses to PARP inhibition in several tumor types, as well as sensitize tumor cells to DNA-damaging chemotherapy." (PMID 35205643, 2022). "We observed that ATR or CDC7 inhibition led to increased DNA damage in tumor cells, as measured by γH2AX staining." (PMID 34663432, 2021). "Overexpression of CDC7 was significantly correlated with a higher tumor recurrence rate (p < 0.001), and shorter OS time (p < 0.001)." (PMID 34881526, 2021). "PHA-767491 hydrochloride is a first-generation CDC7 inhibitor with well-characterized anti-tumor activity." (PMID 27891063, 2016). "PHA-767491 hydrochloride is one of the first-generation CDC7 inhibitors, and its anti-tumor activity is well characterized." (PMID 27891063, 2016). "A higher expression in the tumor relative to normal tissue was particularly evident for CDC7 in its increased 2-ΔΔCt value." (PMID 25475780, 2015). "Preclinical data show that Cdc7 is a novel and promising target for tumor-cell killing, as has been shown with different inhibitors." (PMID 26208856, 2015). "In addition, this study does not include preclinical experimentation to conclude that the anti-tumor activity of CDC7 inhibitors is decreased in an in vivo setting." (PMID 37378325, 2023). "We found that inhibition of CDC7 suppressed tumor cell progression." (PMID 37517032, 2023). "Finally, according to our HCC cohort, we found the expression of CDC7 was highly correlated with tumor size and TNM stage of HCC patients, and patients with higher CDC7 expression had a shorter overall survival." (PMID 36609254, 2023). "The increased expression of CDC7 has been linked to HER2-Enriched and triple-negative subtypes, accelerated cell cycle progression, arrested tumour differentiation and genomic instability during the tumorigenesis of mammary tissue and led to poorer disease-free survival." (PMID 35708873, 2022). "In summary, our data suggest that CDC7 may be an excellent tumor biomarker, and its clinical application warrants further study." (PMID 33763482, 2021). "Additionally, overexpression of CDC7 can also promote tumor cell tolerance and survival by multiple pathways." (PMID 33763482, 2021). "Moreover, a CDC7 inhibitor synergistically enhances the anti‐tumor effect of oxaliplatin in CRC models, demonstrating the potential utility of targeting the PLK1‐MYC‐CDC7 axis in the treatment of oxaliplatin‐based chemotherapy." (PMID 34881526, 2021). "Moreover, for patients with low replication stress tumors, addition of CDC7 inhibitor will possibly result in increased replication stress and thereby sensitize tumor cells to ATR or CHK1 inhibitors." (PMID 34663432, 2021). "The present study showed a positive correlation between CDC7 expression and tumor grades." (PMID 29339028, 2019). "Moreover, a link between Cdc7 expression and the tubular histological tumor type was seen (p < 0.0001)." (PMID 26208856, 2015). "However, when comparing Cdc7 expression and tumor grade and stage, results in both studies opposed each other." (PMID 26208856, 2015). "Furthermore, genetic depletion of CDC7 using small interfering RNA (siRNA) significantly enhanced the anti‐tumor effect of Olaparib in both colony formation and cell proliferation, which was further confirmed with short hairpin RNA (shRNA) targeting CDC7." (PMID 39412086, 2024).
tumor (continued). "Both DBF4 and CDC7 may be potential diagnostic and prognostic markers for HCC, and high expression of DDK members predicts a worse prognosis in patients with HCC, which may be associated with high tumor cell proliferation rate." (PMID 36609254, 2023). "CDC7 overexpression may drive tumor proliferation in various malignancies, by suppressing DDR-mediated cell senescence and preventing DNA damage–induced apoptosis; overexpression has been associated with poor clinical outcomes and may contribute to acquired resistance to chemotherapy." (PMID 36970056, 2022). "Combined CDC7 and CDK8 inhibition significantly reduced proliferation and colony-forming ability, led to ≥4 N DNA content, and reduced tumor volume and mass in vivo." (PMID 42031714, 2026). "Crucially, oxaliplatin resistance in CRC cells was overcome by pharmacological inhibition of CDC7 with the CDC7 inhibitor XL413, which additionally avoided tumor ball formation, clone creation, and cell proliferation." (PMID 40136426, 2025). "Through high‐throughput drug screening with a cell cycle kinase inhibitor library, XL413, a potent cell division cycle 7 (CDC7) inhibitor, is identified which can synergistically enhance the anti‐tumor efficacy of Olaparib." (PMID 39412086, 2024). "CDC7 inhibition by simurosertib restores proteasome activation and MYC degradation; in a low-MYC state, tumor cells are unable to progress through NE transformation, leading to extended treatment response." (PMID 39054323, 2024). "In this present study, we firstly comprehensively analyzed the expression of DBF4 and CDC7 in HCC patients, and found both of them were highly expressed in HCC tumor tissues." (PMID 36609254, 2023). "Dumbbell former 4 (DBF4) complexes with cell division cycle 7 (CDC7) to form DBF4-dependent kinase (DDK), playing instrumental roles in tumor cell survival, whereas its roles in HCC remain elusive." (PMID 37497004, 2023). "Western blot showed that the protein expression of CDC7 and MCM2(pSer53) were down-regulated in tumor sample treated by dequalinium." (PMID 36426371, 2022). "Five genes namely ZWINT, CDC7, MCM4, MCM2 and MCM6 are proposed from the comprehensive computational analysis which gets affected in neoplasia stage and are responsible for the disease progression." (PMID 30150654, 2018). "Upregulated BUB1B, CCNB1, CDC7, CDC20, and MCM3 in HCC tumor tissues also contributed to worse DFS in HCC patients (Log rank P = 0.000052, 0.0192, 0.0307, 0.00496, and 0.0284, respectively)." (PMID 30363964, 2018). "BUB1B, CCNB1, CDC7, CDC20, and MCM3 were all overexpressed in HCC patients with neoplasm histologic grade G3-4 compared to those with G1-2 (all P < 0.05)." (PMID 30363964, 2018). "BUB1B, CCNB1, CDC7, CDC20, and MCM3 were significantly increased in HCC patients with neoplasm histologic grade G3-4 compared to those with G1-2 (all P < 0.05)." (PMID 30363964, 2018). "Our new finding will provide valuable information for a specific type of adjuvant combination therapy that combines the inhibitors of Cdc7, HSP90, and/or ATR to block DNA synthesis and exploit defects in DNA repair/checkpoint of tumor cells." (PMID 29209046, 2017). "In the tumor group, statistic ally-significant high mRNA expression levels of ADAM15 and CDC7 were consistently detected by using the qRT-PCR (p<0.001 and p<0.001, respectively), thus showing excellent agreement with the microarray data." (PMID 25475780, 2015).
tumor (continued). "In order to test whether our results may be extendable to other NE tumor types, we leveraged again the CCLE transcriptomic dataset to assess the correlation between CDC7 mRNA expression and NE phenotype." (PMID 39054323, 2024). "CDC7 inhibition markedly extended response to targeted therapy in two prostate in vivo models of adenocarcinoma-to-NE transformation and a combined NSCLC/SCLC PDX derived from a T-SCLC tumor." (PMID 39054323, 2024). "Both combinations showed consistent efficacy, suppressing tumor growth and substantially extending response to chemotherapy, independent of basal CDC7 expression levels, and without evident additional toxicity." (PMID 39054323, 2024). "The significant different expression of CDC7 in HCC tumor tissues comparision with non-tumor tissues pointed out a beautiful window for HCC treatment." (PMID 37153782, 2023). "CDC7 expression is upregulated in HCC tumor tissues relative to paired non-tumor tissues, which provides a potential therapeutic window for cancer treatment." (PMID 34663432, 2021). "Spearman's correlation test showed that CDC7 expression was correlated with tumor grades (p = 0.000), but not with tumor stage or patient's age and gender (p > 0.05)." (PMID 29339028, 2019). "Additionally, we explored the expression of DBF4 and CDC7 from the expression profiles from GSE25097, GSE54236 and GSE64041, in which both of them were higher expressed in HCC tumor tissues compared with adjacent normal tissues and minimum expressed in healthy normal livers." (PMID 36609254, 2023). "Cdc7 expression levels were not related to tumor localization (p = 0.2093)." (PMID 26208856, 2015).